CEBPA-DT (CEBPA divergent transcript)
Synonyms: ADINR; CEBPA-AS1
Gene: Long non-coding RNA gene on chromosome 19 (33,301,754 to 33,305,254, forward strand). Ensembl gene ENSG00000267296.
Diseases named in the same sentence as CEBPA-DT in open-access papers:
CEBPA-DT is named in the same sentence as 1 disease in open-access papers, as found by Europe PMC text mining. Sharing a sentence is not in itself a finding about the gene and the disease.
CEBPA-DT shares sentences with these, for which no sentence is quoted: schizophrenia (1 paper).